SMAD4 (SMAD family member 4)
Diseases named in the same sentence as SMAD4 in open-access papers (continued):
Sharing a sentence is not in itself a finding about the gene and the disease.
glioma (continued). "Smad4 and EMT-related proteins were differentially expressed in glioma cells with different invasive capacities." (PMID 35251569, 2022). "In glioma SHG44 and U87 cell lines, we used immunoblotting to analyze the expression changes of EMT-related index proteins and Smad4 protein after VPA treatment." (PMID 35251569, 2022). "Immunohistochemistry was used to detect the differences in the expression of Smad4, TIF1-γ, and TGF-β proteins in 39 glioma clinical specimens from the Department of Pathology of our hospital." (PMID 35251569, 2022). "To better understand the role of Smad4 protein in the TGF-β pathway, we analyzed the expression of Smad4, TIF1-γ, and TGF-β proteins in 39 glioma specimens from the Department of Pathology of our hospital using immunohistochemistry." (PMID 35251569, 2022). "SMAD4, the common transducer of TGF-β and bone morphogenic protein pathways, and its downstream target PAI-1, both involved in glioma invasion and angiogenesis, were upregulated in nearly all foci." (PMID 32680567, 2020). "Ectopic expression of miR-146a inhibited SMAD4 and another tumor-suppressor, MMP9, in microglia, and inhibited microglia migration towards glioma-conditioned medium." (PMID 31133802, 2019). "MiR-124-3p inhibits glioma cell proliferation by blocking the expression of STAT3, iASPP, Smad4, and Nur77." (PMID 31708690, 2019). "It has been shown that the TGFβ level is elevated in higher grades of gliomas and its signaling pathway regulates tumor progression through phosphorylation of SMAD2 and SMAD3, which form a complex with SMAD4 to regulate target gene transcription." (PMID 29861845, 2018). "To further validate that SMC4-mediated glioma cell aggressiveness takes place through TGFβ activation, we blocked the TGFβ pathway in SMC4-overexpressing cells by transfecting the cells with Smad4 siRNA or the TGFβ inhibitor LY2157299 monohydrate." (PMID 28287612, 2017). "Thus, SMAD4 might be an independent predictor of survival for glioma patients." (PMID 21791112, 2011). "We found a decreased trend of both SMAD4 protein level and mRNA level from WHO grade I to WHO grade IV glioma." (PMID 21791112, 2011). "Therefore, it was necessary to verify the relationship between Smad4 and EMT in glioma cells to confirm the role of this protein in the invasion and metastasis of tumor cells." (PMID 35251569, 2022). "From the results of real-time PCR, we further clarified that, at the mRNA level, Smad4, N-cadherin, and VPA have an impact on the EMT process in both glioma cell lines after treatment with different VPA doses (control, 1.2, 2.4, and 5 mmol/1) and for different times (0, 12, 24, and 48 hours)." (PMID 35251569, 2022). "During the follow-up period, 197 of the 252 glioma patients (78.2%) had died (108 from the SMAD4-negative group and 142 from the SMAD4-positive group)." (PMID 21791112, 2011). "Interestingly, we found that AMPK scores were significantly negatively correlated with TF expression levels in glioma: E2F4 (rho = − 0.48, P < 0.0001), EZH2 (rho = − 0.57, P < 0.0001), FOXM1 (rho = − 0.49, P < 0.0001), SMAD4 (rho = − 0.18, P < 0.0001) and SUZ12 (rho = − 0.23, P < 0.0001)." (PMID 32807122, 2020). "Moreover, we reviewed clinical information of these SMAD4-positive or -negative glioma patients." (PMID 21791112, 2011).
metastatic tumors (29 papers, 2011 to 2025). "The Cdkn2a/b deletions were highly concordant between primary and metastatic tumors and they mirrored the genetic association of SMAD4 alterations with homozygous CDKN2A/B deletions in the MSK-IMPACT cohort of human PDAC." (PMID 40999053, 2025). "The SMAD4 gene is frequently mutated in PCa, correlates with changes in altered histopathological transitions, metastatic disease, and poor prognosis and is associated with a higher mortality rate in patients receiving anti-EGFR/Akt/mTOR therapy." (PMID 38329726, 2024). "This case also had mutations for APC, KRAS and SMAD4 which were identical in the primary and metastatic tumours." (PMID 37670299, 2023). "In a study performed on primary and metastatic tumor pairs, SMAD4 mutation was one of the frequent novel mutations in metastases; the finding that suggests SMAD4 is involved in clonal divergence." (PMID 28267766, 2017). "We also performed univariate and multivariate Cox regression analyses of the association of SMAD4 mutation status and other factors with OS in patients with metastatic disease." (PMID 28267766, 2017). "A separate study also indicated that patients with mutations of DPC4 showed widespread metastatic disease compared to the more locally destructive disease of PDAC observed from patients with wild-type Smad4." (PMID 24340014, 2013). "Based on the data presented in thisstudy, we propose three SMAD4-mediated processes that may contributeto CRC progression toward metastatic disease, although we cannot excludethe possibility that loss of SMAD4 influences other pro-metastaticprocesses as well." (PMID 36450103, 2023). "While Smad4 inactivation in the premalignant pancreas facilitated the formation of primary tumors, Smad4 reactivation in metastatic disease suppressed liver metastases but promoted lung metastases." (PMID 40999053, 2025). "At the late stage, primary and metastatic tumors expressed the fluorescent reporters and maintained potent depletion of SMAD4 protein." (PMID 40999053, 2025). "In this study, we took advantage of a murine model that enables inducible and reversible Smad4 inactivation at different PDAC stages to interrogate the ongoing need for Smad4 inactivation in metastatic disease." (PMID 40999053, 2025). "The mutational frequencies of CDKN2B (14.8% vs. 0%, p = 0.001), FAT3 (7.4% vs. 0%, p = 0.041), MTAP (13% vs. 1.6%, p = 0.023), and SMAD4 (31.4% vs. 15.6%, p = 0.049) in metastatic tumors were significantly higher than that in primary tumors." (PMID 35664782, 2022). "In the case of lung-specific oligometastatic CRC, analysis of primary and metastatic tumors reveals a decrease in the tumor mutation burden (TMB), regressive mutations in K-Ras, and SMAD4, and scarce T cell infiltrate." (PMID 34204435, 2021). "We show that loss of KRAS and SMAD4 mutations characterizes the oligo-metastatic disease while a progressive mutational evolution (gain in KRAS, PI3KCA, BRAF and SMAD4) is observed in poly-metastatic evolving disease." (PMID 33096795, 2020). "Identical RUNX3/SMAD4 profiles were seen in the primary and metastatic tumors of 5/14 (35.7%) cases." (PMID 29100342, 2017). "Biopsies or resected tissues from metastatic sites were available for 14/121 patients and the whole tissue sections of the 14 metastatic tumors were subjected to SMAD4 and RUNX3 immunohistochemistry." (PMID 29100342, 2017). "While 11/14 (78.6%) of the cases showed concordant SMAD4 expression status between the matched primary and metastatic tumors, only 6/14 (42.9%) cases showed concordant RUNX3 expression status." (PMID 29100342, 2017).
metastatic tumors (continued). "To determine whether metastatic tumors are dependent on SMAD4 inactivation, we developed a mouse model of PDAC that enables spatiotemporal control of Smad4 expression." (PMID 40999053, 2025). "Moreover, while no mice from the parental and scrambled KO groups harbored any secondary metastatic tumors, several mice in both the Smad3 and Smad4 groups developed spontaneous liver metastasis." (PMID 38201651, 2024). "Importantly, the mutational frequency of CDKN2B (14.8% vs. 0%, p = 0.001), FAT3 (7.4% vs. 0%, p = 0.041), MTAP (13% vs. 1.6%, p = 0.023), and SMAD4 (31.4% vs. 15.6%, p = 0.049) in metastatic tumors were significantly higher than those in primary tumors." (PMID 35664782, 2022). "The mutational frequencies (metastatic vs. primary) of CDKN2B (14.8% vs. 0%, p = 0.001), FAT3 (7.4% vs. 0%, p = 0.041), MTAP (13% vs. 1.6%, p = 0.023), and SMAD4 (31.4% vs. 15.6%, p = 0.049) in metastatic tumors were significantly higher than in primary tumors." (PMID 35664782, 2022). "In addition, patients with low SMAD4 protein expression in primary tumors more often presented with metastatic disease." (PMID 33509126, 2021). "In addition, only 1/14 (7.1%) of the metastatic tumors had intact SMAD4 expression, and all 8 (100%) cases with discordant RUNX3 status were RUNX3+ in the primary tumor and RUNX3-negative in the matched metastatic tumors." (PMID 29100342, 2017). "All primary tumors showed RUNX3 expression and/or SMAD4 loss; RUNX3-/SMAD4+ status was not seen in any of the primary or metastatic tumors in this analysis." (PMID 29100342, 2017). "In brief, KPC (SMAD4(+/+)) and KPDDC (SMAD4(−/−)) tumors showed increased RUNX3 expression levels and a high metastatic disease burden, and the high expression of RUNX3 was associated with increased metastatic potential of PDACs independent of epithelial-mesenchymal transition." (PMID 29100342, 2017). "Comparison of the primary and metastatic tumors revealed that PPP2R1A (E370X), SETD2 (I1608V), SMAD4 (G382T), and AR splicing site mutations may be specific to liver metastatic cancer." (PMID 27023146, 2016). "The discrepancy in SMAD4 protein expression between tumor sites could i.e. be explained by differing tissue environment conditions and/or genetic intratumoral heterogeneity between primary and metastatic tumors observed in SINETs." (PMID 33509126, 2021). "Comparing our genetic patterns to the pluri-metastatic disease we focused on KRAS and SMAD4." (PMID 32332709, 2020). "Interestingly, out of the 14 matched cases, the RUNX3-/SMAD4+ profile was seen in none of the primary PDACs and also in none of their subsequent metastatic tumors." (PMID 29100342, 2017).
renal fibrosis (29 papers, 2013 to 2025). A final common manifestation of a wide variety of chronic kidney diseases characterized by glomerulosclerosis and tubulointerstitial fibrosis. "It has been suggested that Smad4 deficiency inhibits renal fibrosis, but it can also result in increased kidney inflammation." (PMID 37365530, 2023). "Studies have found that the SUMOylation of SMAD4 induced by SUMO2/3 plays a crucial role in renal fibrosis associated with diabetic nephropathy." (PMID 35707278, 2022). "In contrast, in a hypertensive nephropathy model, USP25 inhibited the TGF-β signaling pathway by suppressing the ubiquitination process of Smad4, delaying renal fibrosis and protecting renal function." (PMID 40225869, 2025). "Other functions included renal fibrosis (SMAD4), renal cell proliferation (PNN), renal cell viability (APP), and hyperplasia (MYC)." (PMID 34063776, 2021). "Smad4, the same as Smad3, promotes fibrogenesis, which was proven by the observation of reduced collagen I expression and inhibited renal fibrosis in the Smad4 knock-out mouse model." (PMID 34327204, 2021). "Mechanistically, deletion of Smad4 inhibits renal fibrosis by suppressing Smad3 promoter activity and blocking the binding of Smad3 to the collagen promoter without affecting its phosphorylation and nuclear translocation." (PMID 32258028, 2020). "It is also reported that the formation of Smad3/Smad4/CDK9 complex drives renal fibrosis during ureteral obstruction." (PMID 32258028, 2020). "Limited evidence has shown a direct role of Smad4 in renal fibrosis due to the lethality of Smad4 knockout mice." (PMID 32258028, 2020). "Our results demonstrated that AICAR markedly suppressed the expression of renal fibrosis proteins and Smad4, and in turn Dor, a specific AMPK inhibitor, accelerated this expression." (PMID 30630477, 2019). "In this study, we examined two critical downstream markers of TGF-β pathway—SMAD2 and SMAD4—involved in the progression of renal fibrosis in DN." (PMID 31390845, 2019). "Our results indicate that PR-619 ameliorates renal fibrosis, which is accompanied by the reduction of Smad4 expression." (PMID 30114247, 2018). "As Smad4 knockout is embryonically lethal, model of conditional Smad4 deletion in tubular epithelial cells can be used to assess its effect in renal fibrosis and inflammation." (PMID 27610006, 2016). "Smad4 exerts its diverse roles by transcriptionally enhancing Smad3-mediated renal fibrosis while inhibiting NF-κB-driven renal inflammation." (PMID 23301086, 2013). "Consistent with previous studies that found that Smad2,Smad3,Smad4 and Smad7 might be involved in TGF-β1-mediated renal fibrosis, our study observed alterations in the phosphorylation activation of Smad2,Smad3,Smad4 and Smad7 in TGF-β1 treated HK-2 cells." (PMID 38195664, 2024). "The expression of genes that promote renal fibrosis (Smad2, Smad3, Smad4, Shh, Dll1) was downregulated, while the expression of genes that inhibit renal damage (Smurf1, Smurf2, Smad1, Smad5, Smad6, Smad7) was increased in the WT+miPEP31 group (PEP1/2) compared with the WT+ cPEP (SCR1/2) group." (PMID 38992718, 2024). "In a mouse model of unilateral ureteral obstruction, CDK9 could also conjugate with Smad3 and Smad4 to form a complex to promote renal fibrosis." (PMID 36313366, 2022). "However, conditional deletion of Smad4 from TECs significantly reduces renal fibrosis in the obstructive kidney." (PMID 32258028, 2020). "TGF-β may specifically regulate renal fibrosis and inflammation via downstream Smad-dependent mechanisms involving Smad3, Smad4, Smad7, and particularly Smad3-dependent non-coding RNAs." (PMID 32258028, 2020). "The finding that AMPK prevented renal fibrosis via Smad4 has been confirmed in a previous study." (PMID 30630477, 2019). "In opposite, deletion of Smad4 inhibits progressive renal fibrosis in vitro and in vivo." (PMID 27610006, 2016).
renal fibrosis (continued). "Therefore, we speculated that the inhibitory effect of AC and marein on renal fibrosis is dependent on AMPK signaling via Smad4." (PMID 30630477, 2019). "However, the role of Smad4 in TGF-β-mediated renal fibrosis is largely unclear." (PMID 24971350, 2014). "SIRT1 induces deacetylation and deactivation of SMAD3 and SMAD4, thereby inhibiting the profibrotic response of TGF- β1 in vitro and in vivo models of renal fibrosis." (PMID 40514411, 2025). "Previous studies have reported that Sirt1 can inhibit renal fibrosis induced by TGF-β1 signal transduction by deacetylating Smad3 and Smad4." (PMID 38446387, 2024). "SMAD4 plays a key role in regulating TGF-β–induced collagen expression and promotes SMAD3-mediated renal fibrosis while activation of EGFR serves as prognostic biomarker during chronic kidney disease." (PMID 37707956, 2023). "In the UUO and I/R models, SIRT1 activation improved renal fibrosis in proximal tubular cells by deacetylating SMAD3 and SMAD4 and blocking the effect of TGF-β signaling on matrix metalloproteinase-7 (MMP-7), which normally cleaves E-cadherin." (PMID 35277012, 2022). "Moreover, the administration of EPE to db/db mice increased the expression levels of p- PKCα/t-PKCα but decreased the expression levels of VEGF and renal fibrosis biomarkers (TGF-β1, collagen IV, p-Smad2, p-Smad3, and Smad4), as shown by Western blot analyses." (PMID 38928391, 2024). "Interestingly, in an unexpected finding, resveratrol interacted with both SMAD3 and SMAD4 simultaneously to prevent the formation of the SMAD3/4 complex via SIRT1, inhibiting SMAD3 phosphorylation and renal fibrosis." (PMID 35277012, 2022). "In this study, we demonstrate that PR-619 suppresses renal fibrosis and reduces Smad4 expression but not the expression of TGF-β receptors, Smad2, or Smad3, in mice with unilateral ureteral obstruction (UUO), a well-established mouse model of renal fibrosis." (PMID 30114247, 2018). "In conclusion, our present study suggested that MA is not only a potential agent for reducing renal fibrosis by directly targeting TGF-β/Smad signaling, but also an effective inhibitor of MyD88 that may be involved in Smad4 nuclear expression or localization and NF-κB signaling." (PMID 34588982, 2021). "Although we could not identify the specific DUB responsible for regulating Smad4 expression, our data suggest that inhibition of DUBs might be a candidate therapeutic treatment to reduce Smad4 expression and prevent renal fibrosis in CKD." (PMID 30114247, 2018). "We found rhubarb extracts suppressed TGF-β/Smad3-mediated renal fibrosis by reducing the TGF-β1, transforming growth factor-β receptor I (TGF-β RI), transforming growth factor-β receptor II (TGF-β RII), Smad2, p-Smad2, Smad3, p-Smad3, and Smad4, meanwhile increased Smad7." (PMID 30271345, 2018). "In addition, even though WP1130 is an inhibitor of USP9X, administration of WP1130 did not suppress renal fibrosis or Smad4 expression in mice with UUO." (PMID 30114247, 2018). "Thus, Smad4 may play a diverse role in renal fibrosis and inflammation and may not be a specific therapeutic target for CKD." (PMID 32258028, 2020).